HIF1A (hypoxia inducible factor 1 subunit alpha)
Diseases named in the same sentence as HIF1A in open-access papers (continued):
Sharing a sentence is not in itself a finding about the gene and the disease.
tumor (continued). "In addition, CSRP2 and HIF-1α exhibited partially overlapping distribution in successive tumour sections." (PMID 29976963, 2018). "In tumor angiogenesis, only HIF-1α is tightly regulated by low-oxygen tension." (PMID 29449553, 2018). "The description of HIF1A as an early marker for tumour development, lead to the assumption that hypoxia could cause decreased RGS2 expression in early PC." (PMID 30467386, 2018). "The elevated level of HIF2α protein was in certain tumor cell types accompanied by downregulation of HIF1α protein levels, indicating that high Notch signaling may drive a HIF1α-to-HIF2α switch." (PMID 29993038, 2018). "Thus, chemoresistance of FaDu tumor cells expressing HIF1α to SN38 can be reversed as a consequence of HIF1α inhibition by MSA." (PMID 29535842, 2018). "As HIF-1α was previously reported to be target of several miRNAs in HCC17–19, we postulated that miR-3662 may exert its anti-tumor function through directly targeting HIF-1α." (PMID 29748591, 2018). "However, in cSCC, our findings clearly demonstrate that HOXA9 plays tumor-suppressive roles and negatively regulates the expression of HIF-1α and its downstream glycolytic genes." (PMID 29662084, 2018). "The pathological results also revealed that NF-κB, CREB and HIF-1α were overexpressed in tumors in a size-dependent manner, which may be the main reason for the tumor size-dependent activity of the D5 mini-promoter." (PMID 29703163, 2018). "Moreover, the hypoxic tumor stroma stabilizes HIF-1α in MDSCs promoting their rapid cellular differentiation into TAMs." (PMID 30619850, 2018). "Exosomal miR-23a may directly target PHD1 and PHD2 in the endothelial cells, within the tumor microenvironment, which further induces the accumulation of hypoxia-inducible factor (HIF)-1α and promotes tumor angiogenesis." (PMID 30577536, 2018). "HIF-1α-dependent immune evasion through the PI3K/AKT pathway is also important to tumour cells." (PMID 29700419, 2018). "Tumor-infiltrating MDSCs, as well as macrophages and tumor cells, were shown to have increased levels of the cell surface protein PD-L1, which was shown to be an HIF-1α target and upregulated by hypoxia." (PMID 29896451, 2018). "Melanocytes are more prone to oncogenic transformation when grown in a hypoxic microenvironment, and this is in part due to stabilization of HIF-1α, because HIF-1α-deficient melanocytes grown in hypoxic conditions show a diminished transformation capacity and delayed tumor growth in vivo." (PMID 30575721, 2018). "Moreover, loss of PGC1α activity leads to loss of antioxidant defense, such as SOD2, leading to ROS-mediated stabilization of HIF1α and subsequent upregulation of tumor-promoting glucose and glutamine metabolism." (PMID 29361779, 2018). "Apart from this, the hypoxic environment within the tumor area may protect tumor cells from anti-tumor immunity by HIF-1α-dependent upregulation of PD-L1 on cancer cells, which inhibits PD-1 expressing T effector cells." (PMID 29434587, 2018). "However, more studies will be needed to understand the downstream cell signaling pathways, functional consequences, target genes, and suppression of HIF-1α to develop novel treatments or to inhibit tumor progression." (PMID 30560881, 2018). "Indeed, STAT3 phosphorylation increases expression of HIF1α by inhibiting HIF1α degradation in tumor cells." (PMID 29518129, 2018). "In addition, we observed higher levels of HIF-1a expression at both cytoplasmic and nuclear location in subcutaneously implanted tumour cells of HCC cells and hepatic stellate cells together or HCC-TGM2 OE cells alone, compared with respective control groups." (PMID 30393774, 2018). "Various researchers have targeted inhibition/silencing of HIF-1α to improve tumor treatment." (PMID 30200336, 2018).
tumor (continued). "In light of the current findings, future exploration of the major cell lineage subsets in which the presence of OSA induces the increased expression of HIF-1α would be of potential interest to the understanding of the dynamic underpinnings regulating tumor growth and metastatic potential." (PMID 29755400, 2018). "Additionally, hypoxic tumor regions stabilize HIF-1α, which in turn upregulates CXCR4 to further increase the chemotactic responsiveness of TAMs and MDSCs." (PMID 30619286, 2018). "While high HIF-1α levels correlated to low tumor stage and associated with favorable patient prognosis, high HIF-2α expression strongly correlated to unfavorable prognosis and high tumor stage." (PMID 29032465, 2018). "Activation of HIF1A under hypoxia leads to a decrease of HR function; therefore, POLE-category tumours may compromise HIF1A activity via somatic mutations in itself and related genes to maintain the function of HR repair." (PMID 29880869, 2018). "Therefore, improving oxygen levels in tumor tissues and downregulation of HIF-1α has been correlated with improved treatment in chemotherapy, photodynamic therapy and radiotherapy." (PMID 30200336, 2018). "For HIF-1α this was difficult as previous studies have varied widely from considering >10% staining of any intensity as positive, to defining only tumours with over 50% of cells strongly stained as positive." (PMID 29235571, 2018). "We analyzed bioinformatics data and identified three TFs, nuclear factor kappa-light-chain-enhancer of activated B cells (NF-κB), cyclic AMP response element binding protein (CREB), and hypoxia-inducible factor-1α (HIF-1α), that are highly active in tumor cells." (PMID 29703163, 2018). "We showed that depletion of ABCG1 reduced HIF-1α around the necrotic area of a tumor." (PMID 30364132, 2018). "However, the outcome of the therapies is dependent on many parameters, including the frequency of tumour-infiltrating lymphocytes, which inversely correlates with the glycolytic rate and HIF1-α expression." (PMID 29362402, 2018). "Oxygen-containing MNBs may enhance the therapeutic efficiency of photodynamic therapy by degrading HIF-1α and increasing the generation of the ROS by simultaneously delivering oxygen and photosensitizers to the targeted tumor." (PMID 30200336, 2018). "We determined whether HIF-1α acetylation by TSA affects tumor cell survival via nuclear translocation and binding to the HRE of the VEGF promoter." (PMID 29416751, 2018). "This occurs because tumor cells reprogram cellular metabolism increasing the transcription and/or alternative splicing of glycolytic genes induced by the Hypoxia Inducible Factor-1α (HIF-1α), oncogenes and inactivated tumor suppressor genes and distinct growth factors." (PMID 30234009, 2018). "In addition, CSRP2 knockdown inhibited tumour cell invasion under hypoxia with an almost similar magnitude as HIF-1α knockdown." (PMID 29976963, 2018). "Interestingly, in this tumor, EZH2 inactivation is accompanied by increased expression of HIF-1α and anti-apoptotic genes, an effect that then causes multidrug resistance." (PMID 30510924, 2018). "Glycolysis and HIF‐1α formed a feed‐forward loop that stimulated tumour growth and metastases." (PMID 29992789, 2018). "Tumour-derived LOX expression is driven by HIF1-α within hypoxic regions in tumours." (PMID 29098360, 2018). "HIF-1a is a key molecule in the regulation of hypoxia and tumor glycometabolism." (PMID 29789538, 2018). "In addition, activation of HIF-1α activates a number of mechanisms that promote tumor growth, such as immunosuppression, genetic instability, activation of autophagy, increased invasiveness and cancer cell survival." (PMID 29743548, 2018). "However, an enhanced HIF-1α expression was observed for PtCo-treated tumor tissues, implying that PtCo worsened hypoxia in tumor." (PMID 30127408, 2018).
tumor (continued). "In the present study, we investigated whether TSA-mediated HIF-1α acetylation affects tumor cell survival via nuclear translocation and binding to the HRE of the VEGF promoter using HeLa cells for the continuation of our previous study." (PMID 29416751, 2018). "Therefore, by decreasing EAF2 expression, EZH2 reduces VHL activity stabilizing HIF-1α expression, which is an effect that, in turn, increases tumor growth and metabolism favoring glycolysis." (PMID 30510924, 2018). "For example, laurenditerpenol, thyrsiferol, and caulerpin showed the capacity to inhibit the transcription factor HIF-1 by blocking the induction of the oxygen-regulated HIF-1α protein, which promotes tumor cell adaptation and survival under hypoxic conditions." (PMID 30127738, 2018). "Finally, immunohistochemistry results indicated that the expression levels of Snail, VE‐cadherin, MMP2 and HIF‐1α were reduced in tumours with TP53INP1 overexpression, and the expression of E‐cadherin was increased." (PMID 29655255, 2018). "Deletion of HIF-1α or HIF-2α may be insufficient to overcome the strong tumor promoting effect of PTEN deletion." (PMID 30575721, 2018). "HIF-1α is a critical transcription factor implemental in regulating diverse cellular responses to hypoxia, inducing expression of multiple target genes that drives aberrant proliferation and invasion during tumor progression." (PMID 29100347, 2017). "Moreover, we show that HIF-1α KO NK cells are less present in hypoxic zones, suggesting a failure to infiltrate or survive particularly in hypoxic tumours." (PMID 29150606, 2017). "Moreover, mRNA expression of HIF-1-α target genes are upregulated in tumor spheroids cultured under hypoxia." (PMID 28358364, 2017). "In addition, overexpression of mutant IDH2 (R172G) in glioma cells induces nuclear accumulation of β-catenin and upregulation of HIF-1α (hypoxia-inducible factor-1α) signaling that were closely related with tumor invasion and chemoresistance." (PMID 29207533, 2017). "Increasing evidences have been shown that tumor-secreted EVs, containing DNA, RNA, proteins, and other molecule components, such as hypoxia-inducible factor-1α (HIF1α), are capable of mediating cell-cell communication and playing an essential role in inducing metastasis." (PMID 29197379, 2017). "TLR4-induced HIF-1α may be involved in tumor immune escape as well, providing a new concept for the further analysis of HPV pathogenesis." (PMID 29263932, 2017). "Although the differentially expressed genes may represent both direct and indirect targets of GATA3 and HIF-1α, these results support that the GATA3/HIF-1α axis plays an important role in regulating tumour malignancy under hypoxia." (PMID 28263977, 2017). "ICAM-1 was highly co-expressed in HIF-1α positive areas on the tumor cell surface." (PMID 29228586, 2017). "HIF-1α-positive cells (black arrow) were distributed along the tumor (T)-necrosis (N) border only, corresponding to the region containing the vimentin-positive cells (black arrow), as also seen in islands of tissue surrounding vessels within the necrotic region." (PMID 28750639, 2017). "However, HIF1α expression, reflecting hypoxia in tumor tissues, increased over time post-illumination." (PMID 29182023, 2017). "STAT3 and HIF-1α increase the expression of VEGF thus promote tumor angiogenesis." (PMID 28978186, 2017). "However, expression of VEGF, downstream of HIF-1α, is reported to be up-regulated in MPNSTs, suggesting that MPNST is one of the histologic types of tumors in which HIF-1α is responsible for tumor progression." (PMID 28558056, 2017). "Therefore, the collective effects of targeting HIF-1α have more potential for inhibiting tumor growth than does targeting angiogenesis alone." (PMID 27999195, 2017).
tumor (continued). "HIF-1α regulates multiple aspects of tumorigenesis, including proliferation, differentiation, angiogenesis, metabolism, metastasis, and responses to radiation therapy, making it a key regulator of malignant tumor phenotypes." (PMID 28410229, 2017). "Since HDACi, such as MS-275 and SAHA, also target HIF1-α activity (e.g. translation) the combination might produce a synergistic effect by blocking the ability of tumor cells to overcome hypoxic stress induced apoptosis." (PMID 28235409, 2017). "Besides HIF-1α, several regulatory pathways are also known to be involved in the regulation of glucose metabolism in tumor cells, such as Myc, PI3K/Akt/mTOR and AMP-activated protein kinase (AMPK)." (PMID 28886081, 2017). "Acadl expression has been shown to be down-regulated by Hif1α in tumor cells." (PMID 28779178, 2017). "Finally, we revealed that the increased Ang II levels promote the accumulation of HIF-1α in hypoxic tumor cells, and mediates the radiation-resistant phenotype of these cells." (PMID 28205588, 2017). "Overall, our data suggest that exercise-induced differential modulation of Hif1-α and subsequent Hif1 transcriptional activity on tumor metabolism and cell proliferation, may underpin differential tumor sensitivity to exercise in claudin-low breast cancer." (PMID 29254140, 2017). "Although metformin had been shown to increase tumor oxygenation, it remains incompletely understood about whether metformin inhibits HIF-1α-induced angiogenesis by increasing tumor blood perfusion." (PMID 29088755, 2017). "The tumor microenvironment is more acidified at endpoint, presumably due to an accumulation of lactate, which can stabilize hypoxia-inducible factor 1-alpha (HIF-1α) and leads to vascular endothelial growth factor (VEGF) expression, triggering angiogenesis and invasion." (PMID 29216863, 2017). "Furthermore, SIM2 knockdown suppressed tumor growth with increased HIF-1α expression and angiogenesis in vivo." (PMID 29109451, 2017). "Preclinical studies have revealed that Cu-ATSM rapidly diffuses into cells and tissues even in low perfusion areas and is trapped within cells under highly reduced conditions such as hypoxia and that tumor uptake of Cu-ATSM shows good correlation with the HIF-1α expression." (PMID 29179478, 2017). "Hence, targeting HIF1α and HIF2α in tumors would not only suppress the “tumor promoting” actions of these transcription factors but by elevating SPRY2 gene transcription, elevate Spry2 protein levels and, therefore, the tumor suppressing actions of Spry2." (PMID 28196140, 2017). "Here from our work, we found that BA could trigger several of the following effects that are specific to tumor cells: (a) BA could inhibit HIF1α and its downstream target gene VEGF, which may increase angiogenesis in the anaerobic condition." (PMID 29212263, 2017). "Thus, inhibition of HIF-1α expression is deemed as an effective strategy to inhibit the progression and metastases of tumor cells." (PMID 28690762, 2017). "The well-studied oncomiR miR-21, which has been identified as one of the most important miRNAs associated with tumor growth and metastasis, is intricately involved in sustaining the mitogen-activated protein kinases ERK 1/2 signaling pathways and thereby enhances HIF1α and VEGF expression." (PMID 28474282, 2017). "Hence, there is a reciprocal cross talk between the “tumor suppressor”, Spry2, and “tumor promoters”, HIF1α/HIF2α." (PMID 28196140, 2017). "The microenvironment of most solid tumors is hypoxic, and HIF-1α, which is the most important hypoxia-induced transcription factor, has multiple functions in tumor progression, including changes in the aggressive behavior of the tumor." (PMID 28076840, 2017). "HIF-1α is a major regulator of the tumor cell response to hypoxia." (PMID 28467517, 2017). "NOX4 promotes tumor angiogenesis by stabilization of HIF-1α and induction of VEGF expression." (PMID 28594389, 2017).
tumor (continued). "After insufficient RFA, tumor-associated endothelial cells have enhanced angiogenesis and invasiveness of residual HCC, and this may promote tumor angiogenesis via HIF-1α/VEGFA pathway." (PMID 28732507, 2017). "Our results reveal an important mechanism for Parkin in tumor suppression and HIF-1α regulation." (PMID 29180628, 2017). "Analysis of HIF-1α protein expression revealed that the SDHC-mutated cell line contains mixed populations of tumor cells, i.e. 72% were negative for HIF-1α protein expression but about 28% of cells accumulate nuclear HIF-1α even under normoxic conditions." (PMID 28036268, 2017). "Similarly, VHL-mutated PGLs, not those with decreased VHL-gene/mRNA dosage, over-expressed miR-210 and accumulate HIF-1α in most tumor cells." (PMID 28036268, 2017). "Furthermore, tumor expression of carbonic anhydrase IX (CA IX) and hypoxia inducible factor-1a (HIF-1a), surrogates for hypoxia, was significantly lower in the treated group than the control group mice as assessed by IHC and western analysis." (PMID 29206859, 2017). "In addition, SFN significantly reduced HepG2 tumor growth in a modified chick embryo chorioallantoic membrane (CAM) assay, associated with a decrease of HIF-1α and VEGF expression within tumors." (PMID 28978924, 2017). "Our study suggests that high tumor tissue ascorbate level could limit the expression of HIF-1α and its targets in thyroid lesions." (PMID 29084538, 2017). "Furthermore, expression of the HIF1α signature was significantly higher in all HIF2α-HIGH/repair protein-LOW tumor subgroups." (PMID 29156796, 2017). "Moreover to further prove the effect of ACF on hypoxia-related proteins, VEGF, PGK-1 and HIF-1α mRNA levels were quantified in brain extracts from 9L tumor-bearing rats via RT-PCR." (PMID 29097800, 2017). "The HPV-negative tumor cells had only faint staining for HIF-1α under normoxic conditions." (PMID 29163780, 2017). "Hypoxia crucially contributes to genetic instability, intratumoral heterogeneity, malignant progression, tumor stem cell maintenance, sustained angiogenesis, development of treatment resistance, and metabolic reprogramming upon triggering the switch to HIF-1α-dependent phenotypes." (PMID 29312351, 2017). "However, various studies have reported that angiogenesis is induced even during inhibition of HIF-1α during hypoxia, and these findings demonstrate that tumor angiogenesis is also partially recovered by various other factors." (PMID 28053598, 2017). "Our findings strongly support a recent hypothesis where the inflammation amplifier was activated by the stimulation of cytokines, such as TNF-α and IL-6, resulting in the subsequent expression of tumor-related genes such as HIF1-α and SOD-230." (PMID 28801561, 2017). "Therefore, a recent study showed that HIF-1α is an indicator of tumor progression, metastasis, and poor patient prognosis." (PMID 27906669, 2017). "HIF-1α WI was higher in the tumor areas when compared with adjacent normal tissue." (PMID 28272508, 2017). "In addition, it has been reported that HIF‐1α activity is necessary for the influx of BMDCs into the tumour microenvironment after RT." (PMID 29084756, 2017). "Furthermore, they revealed that HIF-1α expression in tumor cells was an independent prognostic marker for patients with locoregional or metastatic ESCC with multivariate analysis." (PMID 28818096, 2017). "In addition, the combination markedly inhibited tumor growth in vivo, reduced tumorigenicity and expression of mitosis, proliferative, HIF1-α and CAIX markers in NB SH-SY5Y xenografts." (PMID 28235409, 2017). "Furthermore, Treg cells have also been reported to be induced under hypoxic tumor microenvironment, through over activated HIF-1α." (PMID 28348562, 2017). "Then, we analyzed HIF-1α protein expression in PGL tumor tissues (n=46) by immunohistochemistry." (PMID 28036268, 2017).